NOTCH1 (notch receptor 1)
Diseases named in the same sentence as NOTCH1 in open-access papers (continued):
Sharing a sentence is not in itself a finding about the gene and the disease.
cancer (continued). "Notably, PTX/miR-34a@C–HA/C–PEI PCNs effectively downregulated critical oncogenic targets, including Notch1, Snail1, and BCL-2, resulting in reduced cancer cell migration and proliferation." (PMID 40869286, 2025). "Expression analysis of brain metastasis-selective markers (BMSM), including HER2+/EGFR+/HPSE+/Notch1+, showed higher expression levels in CSCs compared to non-stem cancer cells." (PMID 41381440, 2025). "Our recent study has demonstrated that canonical and non-canonical NOTCH1 signaling play distinct roles in cancer resistance." (PMID 41453945, 2025). "In cancer cells, sVASN promoted cell proliferation and migration by upregulating the YAP1/TAZ or mTOR-AKT pathways and it promotes stemness maintenance by regulating Notch1." (PMID 40430053, 2025). "Two examples of genes in which some mutations may contribute to clonal expansions while suppressing progression to cancer include KLF4 in intraductal papillary mucinous neoplasms and NOTCH1 in esophageal cancer." (PMID 40680084, 2025). "CTNNB1 and FBXW7 genes are some of the most altered Wnt pathway genes in OC, while in the Notch pathway the receptors (NOTCH1-4), ligands (such as DLL1, JAG2), as well as the canonical target (HES1), are some of the most dysregulated Notch genes in cancers overall." (PMID 40002854, 2025). "The Cancer Genome Atlas and other studies have identified HRAS, CASP8, and NOTCH1 mutations in human papillomavirus-negative, EGFR-negative HNSCC." (PMID 41463200, 2025). "Given the crucial role of Notch signaling in maintaining cancer stemness, we investigated whether YTHDF1-induced NOTCH1 translation drives stemness in colorectal CSCs." (PMID 41423446, 2025). "Studies showed that high Notch1 expression correlates with poor progression-free survival and worse immunotherapeutic response in recurrent HCC patients, while Notch1 overexpression promotes cancer cell escape by inhibiting CD8+ T cell activation." (PMID 41271562, 2025). "We then looked at the transcript levels of these genes and found that, consistent with the protein levels, the transcription of Notch1, Sox2, and the stem cell marker Aldh1a3 genes were suppressed, while that of Numb was elevated, in response to RAB4A knockdown in RAB4A-high cancer cells." (PMID 39463384, 2024). "Together, these studies suggest that ZMIZ1 might act as a direct transcriptional co-factor for Notch1, and disrupting the Notch1-ZMIZ1 interaction may impact upon tumorigenesis, proliferation and metastasis in various cancers." (PMID 38866828, 2024). "These pathways may be inhibited (GSK-3β 16) or activated (Notch1 10, SRC 15) by ASPH in a cell type-specific manner, leading to heterogeneous responses to ASPH inhibition in different cancer cell lines." (PMID 38817852, 2024). "Burkitt lymphoma and AML cells incubated with low microM concentrations of curcumin exhibit a dose-dependent decrease in markers of cancer stem cells, namely, the ratio of ALDH-positive cells, inhibition of colony formation, and downregulation of Notch1, Gli1, and Cyclin D1." (PMID 38612718, 2024). "The mentioned interplay between Notch1, NF-кB, and VEGF strongly presents them as distinguished targets in constricting cancer cell overgrowth and explains, logically, the concurrent increase or decrease (as in Polycladia Crinita treated groups) of these three mediators in the present study." (PMID 38469406, 2024).
cancer (continued). "Based on these results, we propose that targeting the YY1/GHITM/Notch1 axis could decrease the malignant behaviour of KIRC cells and potentiate antitumour efficacy of cancer therapy, which provides a promising and novel therapeutic strategy for KIRC patients." (PMID 38588015, 2024). "Notably, both studies identified signaling pathways (such as Notch1 in the current study and JAK/STAT from the previous study) that play a pivotal role in cell growth, differentiation, and immune responses in cancers." (PMID 38892393, 2024). "Various cancer cells were treated with TP and each signaling inhibitor to determine whether TP affects cell viability by inhibiting STAT3 and Notch1 signaling." (PMID 38731894, 2024). "We further validated the interaction of NOTCH1 with histone deacetylase 1 or GATAD2B using protein network analysis, proximity-based ligation, in vivo cross-linking and coimmunoprecipitation assays in several Notch-addicted cancer cell lines." (PMID 38043798, 2024). "For instance, the expression of Notch-1 and miR-21 were found to have a positive correlation with the development of CRC, suggesting that miR-21 may function to promote cancer progression." (PMID 38279330, 2024). "The potential therapeutic value of co-targeting ERK1 and Notch1 has already been demonstrated in cancer but not RA." (PMID 38272919, 2024). "In our meta-analysis, we identified six genes with high mutation prevalence in brain metastases, of particular interest for their potential role in brain metastatic process and resistance to first-line anti-cancer drugs: ESR1, ERBB2, EGFR, PTEN, BRCA2 and NOTCH1." (PMID 36980614, 2023). "Moreover, inhibiting the Notch signaling via NOTCH1 knockdown reversed IGF2BP3‐induced expression of genes related to p‐EMT and cancer cell plasticity." (PMID 37171793, 2023). "Besides, research concentrating on reprogramming CAFs has pointed out that when CAFs were exposed to apoptotic cancer cells, apoptotic cancer cells reprogramed CAF through the Notch1-WISP-1 signaling pathway, inhibiting cancer invasion and metastasis." (PMID 37784082, 2023). "Withaferin A was highly effective in eliminating cancer stem cells (CSC) that expressed cell surface markers, such as CD24, CD34, CD44, CD117, and Oct4 while downregulating Notch1, Hes1, and Hey1 genes; however, mice treated with cisplatin alone experienced the opposite effects on the cells." (PMID 37259311, 2023). "Notably, miRNAs that in our experimental model were found in EVs, are associated with many signaling pathways that are de-regulated in cancer, such as PI3K/AKT, JAK/STAT, NOTCH1, Ras, and ERK." (PMID 36769076, 2023). "During such a reversion, cancer cells re-express several previously repressed genes, including those involved in cell plasticity (Oct4, SOX-2, and Nanog), while genes (PSEN1, Notch-1) and proteins (SNAI1, αSMA, N-cadherin) supporting epithelial–mesenchymal transition (EMT) are downregulated." (PMID 37511359, 2023). "We showed that genetic KO and pharmacological inhibition of Cbl-b prevents Notch1 degradation in response to adenosine and reactivates its signaling, thus resulting in enhanced CD8+ T-cell effector functions, anti-cancer response and resistance to immunosuppression." (PMID 36090975, 2022). "In addition to NOTCH1, NOTCH3 signaling was also considered to be important in several types of cancers." (PMID 35900231, 2022). "Moreover, this synergistic effect of the combination of luteolin and curcumin was also observed in the protein expressions of Notch1 and TGF-β in CL-188 cells and xenograft tumors, which is in line with the anti-cancer effect in cells and tumors." (PMID 35740666, 2022).
cancer (continued). "In addition to blockage of the SHH signaling pathway, ATO downregulates Notch signaling by decreasing the levels of Notch1 and Hes1 proteins having an inhibitory effect on GBM cancer stem-like cells in vitro and in vivo." (PMID 36010607, 2022). "We also confirmed that Cbl-b inhibitors did not affect Notch1 in cancer cell lines, including C0321, and cancer cells in organoids." (PMID 36090975, 2022). "The fine-tuned regulation of NOTCH1 activity makes oN an excellent tool to study the role of Notch signaling in embryogenesis, cancer biology, and drug resistance." (PMID 35585598, 2022). "Based on our data, activated forms of Notch1, Notch2, Notch3, and Notch4 (N1ICD, N2ICD, N3ICD, and N4ICD) in stomach-cancer cells were all upregulated, especially N1ICD and N2ICD, after the co-culture of cancer cells and macrophages." (PMID 35382168, 2022). "The results showed that the expression of NOTCH1 was not always consistent in different cancers compared with their normal tissues by using the TIMER database." (PMID 36119057, 2022). "By extension, silencing NOTCH1 in BT-549 cells was similarly associated with inhibition of tumorsphere formation, indicating that MUC1-C–induced regulation of NOTCH1 chromatin accessibility and expression contributes to the CSC state in different types of carcinoma cells." (PMID 35022313, 2022). "Moreover, it was also demonstrated that low doses of DOX when combined with a nanosystem inhibited Notch1 and Ras/MAPK pathways, decreased cancer stem cell population, and reduced tumorigenesis as compared to free DOX in both in vitro and in vivo settings." (PMID 34063119, 2021). "Additionally, TUG1 can also exert its oncogenic role via sponging tumoral suppressor microRNAs or modulating cancer-related signaling pathways like Wnt, MAPK, or Notch1." (PMID 33747256, 2021). "In contrast, elevation of elevation of the NOTCH1 downstream target HES1 correlated significantly with increased numbers of myeloid-derived stem cells (MDSC), TAMs, and T-regulatory cells (Treg) in the mouse cancer tissues." (PMID 34944837, 2021). "Notch1 and EGFR are two surface receptors activating different cellular processes in cancer cells." (PMID 33922104, 2021). "In addition, inhibiting Notch-1 in ATC cells drastically reduced the expression of key markers representing epithelial to mesenchymal transition and cancer cell stemness." (PMID 33669363, 2021). "These regions contain important cancer-related genes including TRIM28, SEMA3C, NOTCH1, and FAT1." (PMID 34168152, 2021). "Alternatively, in already transformed cancer cells and particularly in SCC cancer cells, USP28 acts as an oncoprotein facilitating cancer homeostasis and proliferation via stabilization of oncogenic substrates, such as c-MYC, c-JUN, NOTCH1, ∆Np63, and CCNE." (PMID 34685632, 2021). "Importantly, 2-DG, but not the OXPHOS inhibitor oligomycin greatly reduced the ability of Notch1 and TAZ to promote cancer cell proliferation." (PMID 34482375, 2021). "The activation of NOTCH1 is, in fact, able to induce HES1 and to start cancer progression." (PMID 33672900, 2021). "Whether triptonide directly binds to Twist1 and Notch1 proteins in TNBC and other cancer cells remains to be determined." (PMID 34922602, 2021). "Although the Notch signaling has been clarified to be involved in the progression of various cancers, the correlation of Notch1 and PLK2 has not been investigated." (PMID 33176854, 2020).
cancer (continued). "Specific blocking of Notch1 activation with therapeutic antibodies such as mAb WC613 targeting the EGF-repeat region or OMP-52M51 targeting the LNR and HD region of Notch1 have shown significant efficacy for in vitro as well as in vivo cancer models." (PMID 32630477, 2020). "The similar effects of DBZ treatment and NOTCH1 silencing on cultured CAFs and on SCC/CAF co-cultures suggested that this compound could also be beneficial in vivo, for suppression of cancer/stromal cell expansion." (PMID 33046701, 2020). "Recently, the non-canonical stimulation of NOTCH1 has also been correlated with tumorigenic events in various cancers." (PMID 32792479, 2020). "There is no differentiation in the expression of the Notch1 gene before cancer, and it is also expressed in non‐lesion sites." (PMID 31976596, 2020). "The CTLs are involved in cancer immunosurveillance, and Notch 2, unlike Notch 1, seems to be required for the efficient induction of their antitumoral activity." (PMID 33374160, 2020). "Notch1 signaling increases the DNA binding ability of NF-κB and thereby induces the expression of MMP9, which remodels the extracellular matrix and facilitates the extravasation of several cancer cells." (PMID 32517366, 2020). "Notch1 appears to be in part responsible for maintaining CSC stemness in TNBCs, and the specific inhibition of its signaling has a remarkable inhibitory effect on this cancer subtype, thus increasing the sensitivity of TNBC to chemotherapeutic reagents." (PMID 31379945, 2019). "Therefore, the aim of the present study was to assess the influence of dysregulated Notch1 activity for HDIs and CDDP mediated inhibition of TNBC cancer cell proliferation." (PMID 31357442, 2019). "Inhibition of Notch1 can significantly reduce the binding ability of NF-kappa B to DNA, and the expression and activity of MMP-2 and MMP-9 are also significantly inhibited, thus reducing the metastasis ability of cancer cells." (PMID 30622441, 2019). "Recently, it has been shown that an antibody against the negative regulatory region (NRR) of Notch1 resulted in reduced proliferation, restricted expression of its targets HES1, HES5, and HEY-L, reduced colony forming ability, and lessened cancer stem-like population in MDA-MB-231 cell lines." (PMID 31379945, 2019). "Furthermore, our study demonstrated that low-dose X-NP-DOX inhibited Notch1 and Ras/MAPK pathways, decreased cancer stem cell population, and reduced tumorigenesis compared to free DOX in both in vitro and in vivo settings." (PMID 30691317, 2019). "However, the relationship between the Notch1 signaling pathway and PTC, the most common type of malignant tumor of the endocrine organ, and the regulatory mechanism of its downstream target genes remain undefined." (PMID 30622441, 2019). "Another fact needs special explanation, especially when isobolographically compared the IC50 mix values produced by the same two-drug mixture (i.e., CDDP+SAHA), in the same cancer line (i.e., MDA-MB-231), but with different Notch1 activity (Notch1low vs. Notch1high)." (PMID 31357442, 2019). "Accordingly, embryonic stem cells and cancer cells have been reported to share a common gene expression pattern, and the expression of ESC markers (such as HMGA2, KLF4, NOTCH1, OCT3/4 and SOX9) that are known to play a key role in pluripotency, self-renewal, and cancer, is increased in many tumors." (PMID 29383160, 2017).
cancer (continued). "Inhibition of Notch1 reduces cancer stem cell function, reduces expression of Notch target genes HES1, HES5 and HEY-L, and reduces the population of CD44HiCD24low, a population identified as cancer stem cells." (PMID 28594912, 2017). "Since Pim kinases and Notch1 play important functions in tumorigenesis, it is not surprising that there are major efforts underway to target their activities for cancer therapy." (PMID 27281612, 2016). "In turn, Notch1 activates the IGF-1R pathway, promoting cancer cell survival under hypoxia." (PMID 25653136, 2015). "On the other hand, DTX1 can also positively regulate cell context-dependent non-canonical NOTCH1/2 signaling pathways and NOTCH1/2-independent signaling pathways in cancer." (PMID 26654227, 2015). "In HB2 cells, an immortal but non-cancer derived breast cell line, Notch1-independent MRP1 induction was noted and DAPT did not enhance doxorubicin-induced apoptosis." (PMID 26362310, 2015). "It has been reported that NOTCH1 may regulate the expression of matrix metalloproteinase-9 (MMP9) in prostate cancer cells, which plays key roles in cancer invasion." (PMID 24621612, 2014). "Notch-1 upregulation induced a possible epithelial-mesenchymal transition in U87-MCSF cells, which accounted for an increase in the proportion of CD24high/CD44less cancer stem cells in U87-MCSF cells after 5-FU treatment." (PMID 24391839, 2013). "All cancer cell lines expressed high levels of Notch1 compared with normal biliary epithelial cells." (PMID 23688168, 2013). "NOTCH1 correlated with the expression of various other cancer-related proteins like HIF1A but not with MUC1 as a marker of normal lung physiology." (PMID 23028920, 2012). "Notch1 is known to regulate Snail and Slug mRNA levels, but efforts have not been made to examine alternative functions of NICD and Snail expression in the same cancer cell line." (PMID 22128911, 2011). "Furthermore, the networks related to cell cycle, cancer and nervous system development and function showed that several genes such as Nfkb2, NFκBia, BRCA1, Vegf, Jag2, Notch1, EGR1, FoxS1 and collagen type I were regulated by TNF." (PMID 20967264, 2010). "Both NotchIC and Notch1 lacking the PEST-domain closely resemble NOTCH1 mutants found in human cancers." (PMID 18485879, 2008). "Notch1 associates with these RBPJ binding sites after activation in liver bile duct carcinoma cells, and this interaction may promote Notch1-mediated regulation of POSTN transcription, as the Notch1/RBPJ complex is known to control cell fate decisions, proliferation, and differentiation in cancer." (PMID 41018265, 2025). "The possible apoptotic pathways for anti-cancer effects of curcumin on cell signal transduction include PI3K, Akt, mTOR, ERK5, AP-1, TGF-β, Wnt, β-catenin, Shh, PAK1, Rac1, STAT3, PPARγ, EBPα, NLRP3 inflammasome, p38MAPK, Nrf2, Notch-1, AMPK, TLR-4, and MyD-88." (PMID 41149437, 2025). "Using signatures developed to predict pan-cancer response to immunotherapy, we found angiogenesis, epithelial-mesenchymal transition (EMT), and protumor cytokines to be the most significantly enriched pathways in high compared with low-NOTCH1-expressing tumors." (PMID 40627448, 2025). "Moreover, principal component analysis of single-cell RNA-sequencing data of 65,655 GSCs and 14,207 GBM cells revealed that the area where CYP3A5 was highly expressed harbored cells that also markedly expressed cancer stem cell markers, such as PROM1, SOX2, EZH2 and NOTCH1." (PMID 39754188, 2025). "Notably, NOTCH1 expression was higher in benign tumors compared to precancerous and malignant tumors, whereas FGFR2 expression showed an opposite trend, with higher levels in precancerous and malignant tumors compared to benign tumors." (PMID 39063983, 2024).